DDX28 (DEAD-box helicase 28)
Description:
Plays an essential role in facilitating the proper assembly of the mitochondrial large ribosomal subunit and its helicase activity is essential for this function. May be involved in RNA processing or transport. Has RNA and Mg(2+)- dependent ATPase activity.
Synonyms: MDDX28; FLJ11282
Tractability: Small molecule: a structure with a bound ligand is known. PROTAC: ubiquitination databases record sites on it; its protein half-life has been measured.
Gene: Protein-coding gene on chromosome 16 (68,020,916 to 68,023,232, reverse strand). Ensembl gene ENSG00000182810.
Subcellular location: Nucleus; Mitochondrion; Mitochondrion matrix, mitochondrion nucleoid; Mitochondrion matrix
Subcellular location (Human Protein Atlas): Mitochondria; Cytosol; Nucleoli
Gene Ontology:
Molecular function: RNA binding; rRNA binding; ATP binding; ATP hydrolysis activity; nucleic acid binding; RNA helicase activity
Biological process: mitochondrial large ribosomal subunit assembly
Cellular component: mitochondrial matrix; mitochondrial nucleoid; mitochondrion; nucleolus; nucleus; ribonucleoprotein granule
Genetic constraint (gnomAD): Loss-of-function variants: 26 observed, 28.62 expected, observed/expected ratio (o/e) 0.91, 90% interval 0.67 to 1.26. The upper end of that interval is the gene's LOEUF score, 1.26, which puts it in group 5 of 6, group 1 being the genes least tolerant of losing a copy. Missense variants: 787 observed, 701.86 expected, observed/expected ratio (o/e) 1.12, 90% interval 1.06 to 1.19. Synonymous variants: 368 observed, 312.61 expected, observed/expected ratio (o/e) 1.18, 90% interval 1.08 to 1.28.
Homologues: Orthologues: chimpanzee DDX28 (99% identical), macaque DDX28 (94% identical), pig DDX28 (86% identical), rabbit DDX28 (82% identical), mouse Ddx28 (81% identical), guinea pig DDX28 (80% identical), rat Ddx28 (78% identical), dog DDX28 (69% identical), zebrafish ddx28 (46% identical), Drosophila melanogaster Dbp21E2 (29% identical). Paralogues in human: DDX3Y (25% identical), DDX3X (25% identical), DDX43 (24% identical), DDX5 (24% identical), DDX23 (24% identical), DDX4 (24% identical), DDX17 (24% identical), DDX31 (24% identical), DDX24 (23% identical), DDX53 (23% identical), DDX54 (23% identical), DDX47 (23% identical), and 26 more.
Diseases named in the same sentence as DDX28 in open-access papers:
DDX28 is named in the same sentence as 7 diseases in open-access papers, as found by Europe PMC text mining. Sharing a sentence is not in itself a finding about the gene and the disease. The quoted sentences say what the papers report.
colorectal cancer (4 papers, 2012 to 2021). A primary or metastatic malignant neoplasm that affects the colon or rectum. "Gene expression analyses identified DDX28, among other genes, to be differentially expressed in colorectal tumor tissue and a potential association between expression levels of DDX28 and development and prognosis of early-onset colorectal cancer." (PMID 33917098, 2021). "Although DDX28 has not specifically been reported to have a role in colorectal cancer, other DEAD box RNA helicases have been shown to be overexpressed in colorectal tumors, demonstrating a function for RNA helicases in tumorigenesis." (PMID 22363440, 2012).
glioblastoma (1 paper, 2024). The most malignant astrocytic tumor (WHO grade IV). "Similarly, HIF2α has been shown to regulate GPx1 to ensure resistance to oxidative stress and radiation, while contributing to glioblastoma progression via various mechanisms such as the DDX28-mediated regulation of eIF4E2-driven translation." (PMID 38893207, 2024).
preeclampsia (1 paper, 2025). Preeclampsia is a hypertensive disorder of pregnancy that is characterized by new-onset hypertension with proteinuria presenting after 20 weeks of gestation, and depending on mild or severe forms may initially present with severe headache, visual disturbances, and hyperreflexia. "qRT-PCR confirmed that GLUL and NCL expression decreased and DDX28 and RIOK1 expression increased in clinical placental samples of preeclampsia group." (PMID 40552285, 2025).
tumor (3 papers, 2012 to 2023). "For rs9929218 at 16q22.1, two genes were observed to have a difference in expression levels by genotype: nucleolar protein 3 (NOL3; q-value = 0.017) and DEAD box polypeptide 28 (DDX28, q-value = 0.046), in adjacent normal but not tumor tissue." (PMID 22363440, 2012). "The Spearman's Rank Order correlation coefficients for the four genes identified in the cis-eQTL analysis in the tissue type (tumor or normal) where genotype-specific differential expression was observed were, ATP5C1 rs = 0.39; DLGAP5 rs = 0.68; NOL3 rs = 0.11; DDX28 rs = 0.22." (PMID 22363440, 2012).
DDX28 also shares sentences with these, for which no sentence is quoted: colorectal tumor (2 papers); breast carcinoma (1); cancer (1).